THOC1 (THO complex subunit 1)
Description:
Component of the THO subcomplex of the TREX complex which is thought to couple mRNA transcription, processing and nuclear export, and which specifically associates with spliced mRNA and not with unspliced pre-mRNA. Required for efficient export of polyadenylated RNA. The THOC1-THOC2-THOC3 core complex alone is sufficient to bind export factor NXF1-NXT1 and promote ATPase activity of DDX39B/UAP56. TREX is recruited to spliced mRNAs by a transcription-independent mechanism, binds to mRNA upstream of the exon-junction complex (EJC) and is recruited in a splicing- and cap-dependent manner to a region near the 5' end of the mRNA where it functions in mRNA export to the cytoplasm via the TAP/NXF1 pathway. Regulates transcriptional elongation of a subset of genes. Involved in genome stability by preventing co-transcriptional R-loop formation (By similarity). May play a role in hair cell formation, hence may be involved in hearing (By similarity). Activates a G2/M cell cycle checkpoint prior to the onset of apoptosis. Apoptosis is inhibited by association with RB1. (Microbial infection) The TREX complex is essential for the export of Kaposi's sarcoma-associated herpesvirus (KSHV) intronless mRNAs and infectious virus production.
Synonyms: p84N5; HPR1; P84; DFNA86
Tractability: PROTAC: UniProt records ubiquitination sites on it; ubiquitination databases record sites on it; its protein half-life has been measured.
Gene: Protein-coding gene on chromosome 18 (214,515 to 268,053, reverse strand). Ensembl gene ENSG00000079134.
Subcellular location: Nucleus speckle (Isoform 1); Nucleus, nucleoplasm; Nucleus matrix; Cytoplasm; Cytoplasm (Isoform 2)
Subcellular location (Human Protein Atlas): Nuclear speckles
Pathways (Reactome):
Metabolism of RNA: Transport of Mature mRNA derived from an Intron-Containing Transcript; mRNA 3'-end processing
Gene Ontology:
Molecular function: identical protein binding; protein binding
Biological process: mRNA export from nucleus; signal transduction
Cellular component: chromosome, telomeric region; cytoplasm; nuclear speck; nucleus; THO complex; THO complex part of transcription export complex; transcription export complex; nucleoplasm; nuclear matrix
Genetic constraint (gnomAD): Loss-of-function variants: 16 observed, 44.52 expected, observed/expected ratio (o/e) 0.36, 90% interval 0.24 to 0.55. The upper end of that interval is the gene's LOEUF score, 0.55, which puts it in group 2 of 6, group 1 being the genes least tolerant of losing a copy. Missense variants: 363 observed, 511.91 expected, observed/expected ratio (o/e) 0.71, 90% interval 0.65 to 0.77. Synonymous variants: 196 observed, 177.17 expected, observed/expected ratio (o/e) 1.11, 90% interval 0.98 to 1.25.
Homologues: Orthologues: chimpanzee THOC1 (99% identical), macaque THOC1 (99% identical), dog THOC1 (98% identical), rabbit THOC1 (98% identical), pig THOC1 (96% identical), mouse Thoc1 (96% identical), guinea pig THOC1 (96% identical), rat Thoc1 (94% identical), tropical clawed frog thoc1 (80% identical), zebrafish thoc1 (74% identical), Drosophila melanogaster Hpr1 (39% identical), rat Da2-19 (35% identical), and 1 more.